GMPPB (GDP-mannose pyrophosphorylase B)
Description:
Catalytic subunit of the GMPPA-GMPPB mannose-1-phosphate guanylyltransferase complex. Catalyzes the formation of GDP-mannose, an essential precursor of glycan moieties of glycoproteins and glycolipids. Can catalyze the reverse reaction in vitro. Together with GMPPA regulates GDP-alpha-D-mannose levels.
Synonyms: KIAA1851; LGMDR19; MDDGA14; MDDGB14; MDDGC14
Tractability: Small molecule: a structure with a bound ligand is known. PROTAC: ubiquitination databases record sites on it; its protein half-life has been measured.
Gene: Protein-coding gene on chromosome 3 (49,716,844 to 49,723,985, reverse strand). Ensembl gene ENSG00000173540.
Subcellular location: Cytoplasm
Pathways (Reactome):
Metabolism of proteins: Synthesis of GDP-mannose
Gene Ontology:
Molecular function: mannose-1-phosphate guanylyltransferase (GTP) activity; protein binding; GTP binding; transferase activity
Biological process: GDP-mannose biosynthetic process; GDP-mannose metabolic process; glycoprotein biosynthetic process
Cellular component: cytoplasm; GDP-mannose pyrophosphorylase complex; cytosol
Genetic constraint (gnomAD): Loss-of-function variants: 38 observed, 41.89 expected, observed/expected ratio (o/e) 0.91, 90% interval 0.7 to 1.19. The upper end of that interval is the gene's LOEUF score, 1.19, which puts it in group 5 of 6, group 1 being the genes least tolerant of losing a copy. Missense variants: 436 observed, 498.01 expected, observed/expected ratio (o/e) 0.88, 90% interval 0.81 to 0.95. Synonymous variants: 193 observed, 194.01 expected, observed/expected ratio (o/e) 0.99, 90% interval 0.88 to 1.12.
Gene-disease validity (ClinGen):
ClinGen rates the evidence that GMPPB causes each of these diseases.
myopathy caused by variation in GMPPB (autosomal recessive): Definitive. Any myopathy in which the cause of the disease is a variation in the GMPPB gene.
Homologues: Orthologues: chimpanzee GMPPB (99% identical), macaque GMPPB (98% identical), mouse Gmppb (97% identical), guinea pig GMPPB (97% identical), dog GMPPB (96% identical), rabbit GMPPB (92% identical), tropical clawed frog gmppb (81% identical), zebrafish gmppb (80% identical), Drosophila melanogaster Gmppb (70% identical), pig GMPPB (66% identical), Caenorhabditis elegans tag-335 (63% identical). Paralogues in human: GMPPA (39% identical), EIF2B5 (24% identical), EIF2B3 (20% identical).
Diseases named in the same sentence as GMPPB in open-access papers:
GMPPB is named in the same sentence as 31 diseases in open-access papers, as found by Europe PMC text mining. Sharing a sentence is not in itself a finding about the gene and the disease. The quoted sentences say what the papers report.
dystroglycanopathies (7 papers, 2013 to 2025). "The frequency of GMPPB mutations is estimated to be approximately 5% among patients with dystroglycanopathies, based on a large cohort study from China." (PMID 36833299, 2023). "Differently from other dystroglycanopathies, GMPPB mutations can lead to a defect of neuromuscular transmission and congenital myasthenic syndrome due to altered glycosylation of the acetylcholine receptor subunits and other synaptic proteins." (PMID 36833299, 2023). "Our group subsequently confirmed that variants in both B3GALNT2 and GMPPB can cause dystroglycanopathy." (PMID 23894383, 2013). "Patients with mutations in GMPPB are classified under α-dystroglycanopathies." (PMID 40993721, 2025). "Like other dystroglycanopathies, GMPPB mutations manifest with a spectrum of clinical features of variable severity, spanning from congenital muscular dystrophies (CMD) with brain and eye abnormalities to limb-girdle muscular dystrophies (LGMD) to exercise intolerance and rhabdomyolysis." (PMID 36833299, 2023). "Mutations in GMPPB not only manifest as CMS but also as dystroglycanopathy." (PMID 30808424, 2019). "Hence, mutations in GMPPB result in secondary dystroglycanopathy." (PMID 36833299, 2023). "Thus mutations in GMPPB provide a link between myasthenic syndromes and dystroglycanopathies." (PMID 26133662, 2015). "More recently, it was shown that mutations in GMPPB can also cause CMS and bridge myasthenic disorders with dystroglycanopathies." (PMID 29874875, 2018). "Moreover, the spectrum of glycosylation abnormalities has been increased with the report that GMPPB mutations can cause CMS, thus bridging myasthenic disorders with dystroglycanopathies." (PMID 29874875, 2018). "For example, when P18 and P19 with mutations in B3GALNT2 and P20 and P21 with mutations in GMPPB were first analysed by flow cytometry, variants in these genes had not yet been identified as the cause of a dystroglycanopathy." (PMID 23894383, 2013).
congenital muscular dystrophy (6 papers, 2014 to 2023). A muscular dystrophy that is characterized by diminished muscle tone (hypotonia), progressive muscle weakness and degeneration (atrophy), abnormally fixed joints, spinal rigidity, and delays in reaching motor milestones such as sitting or standing unassisted. "Previous studies have shown that GMPPB mutations correlate with several congenital diseases, including severe congenital muscular dystrophy (CMD) with abnormalities in the brain and eye." (PMID 37834154, 2023). "Here, we report a case of an individual presenting congenital muscular dystrophy with cerebellar involvement, who presents two heterozygous GMPPB mutations (V111G and G214S)." (PMID 35006422, 2021). "At the severe end of the spectrum, mutations in GMPPB lead to the congenital muscular dystrophy with brain and eye abnormalities." (PMID 26133662, 2015). "For example GMPPB mutations may mimic LGMD or congenital muscular dystrophy in cases in which dystrophic features are more prominent than CMS features." (PMID 30808424, 2019). "Recent discoveries of gene associations to diseases, like B3GALNT2, GMPPB and B3GNT1 to congenital muscular dystrophies, were prioritized in the ranked lists, suggesting a posteriori validation of our approach and predictions." (PMID 25353622, 2014). "Two other genes, GMPPB, ranked in 225th, and B3GNT1, ranked in 479th, were also implicated in a form of congenital muscular dystrophy with hypoglycosylation of alpha-dystroglycan and Walker-Warburg disease, respectively." (PMID 25353622, 2014). "The list of candidate genes was further filtered based on expression data and association with other diseases, and the ensuing identification of mutations in high-ranked genes for congenital muscular dystrophies (B3GALNT2, GMPPB and B3GNT1) illustrated the validity of this approach." (PMID 25353622, 2014).
congenital myasthenic syndrome (6 papers, 2015 to 2023). Congenital myasthenic syndrome (CMS) is a group of genetic disorders of impaired neuromuscular transmission at the motor endplate characterized by fatigable muscle weakness. "GMPPB mutations can also lead to the defect of neuromuscular transmission and congenital myasthenic syndrome due to altered glycosylation of the acetylcholine receptor subunits and other synaptic proteins." (PMID 36833299, 2023). "Here we identify a fifth glycosylation gene, GMPPB, where mutations cause congenital myasthenic syndrome." (PMID 26133662, 2015). "GMPPB mutations also cause a related disease called congenital myasthenic syndrome (CMS)." (PMID 36830724, 2023). "One of them, GMPPB, encoding the guanosine-diphosphate-mannose (GDP-mannose) pyrophosphorylase B protein, has recently been associated with a wide clinical spectrum ranging from severe Walker-Warburg syndrome to pseudo-metabolic myopathy and even congenital myasthenic syndromes." (PMID 30257713, 2018). "Interestingly, GMPPB mutations-associated phenotypic spectrum ranges from LGMD, to congenital myasthenic syndrome (CMS), to severe CMD with eye and brain symptoms." (PMID 35006422, 2021).
muscular dystrophy (5 papers, 2015 to 2025). Muscular dystrophy (MD) refers to a group of more than 30 genetic diseases characterized by progressive weakness and degeneration of the skeletal muscles that control movement. "Another pathway under investigation highlights that mutations in glycosylphosphatidylinositol-anchored protein B (GMPPB) can result in a muscular dystrophy variant characterized by low glycosylation of α-dystroglycan (α-DG)." (PMID 41195013, 2025). "In humans, mutations in GMPPA or GMPPB cause congenital disorders of glycosylation and muscular dystrophies." (PMID 40315235, 2025). "GDP-mannose pyrophosphorylase B (GMPPB) loss-of-function is associated with muscular dystrophy and variable additional neurological symptoms." (PMID 38979475, 2024). "Mutations in GMPPB are associated with variable disorders such as muscular dystrophy and other neurological symptoms, including intellectual disability, epilepsy, and cerebellar hypoplasia." (PMID 38979475, 2024). "In the group of congenital muscular dystrophies, 11 patients received a genetic diagnosis with mutations in the following genes: LAMA2 (three cases); POMGNT1 (one case); COL6 (one case); TTN (one case); GMPPB (one case); POMT2 (one case); POMGNT2 (one case); DMD (one case); and SCGA (one case)." (PMID 34675869, 2021).
depression (2 papers, 2021 to 2022). "Several TWAS significant genes were also dysregulated in brains of depression cases compared with controls (including PCDHA8, FANCL, TMEM161B-AS1, GMPPB, STAU1, NDUFA2, GPX1 and PCDHA7), implying that genetic variants may contribute to depression risk by regulating gene expression." (PMID 34021117, 2021). "Interestingly, five TWAS significant genes (TMEM161B-AS1, GMPPB, STAU1, NDUFA2 and GPX1) were significantly upregulated in brains of depression cases compared with controls in GSE102556 dataset." (PMID 34021117, 2021).
epilepsy (2 papers, 2023 to 2024). A brain disorder characterized by episodes of abnormally increased neuronal discharge resulting in transient episodes of sensory or motor neurological dysfunction, or psychic dysfunction. "To date, fewer than 15 patients have been described with GMPPB deficiency and mostly displayed severe muscle phenotypes, hypotonia, microcephaly, epilepsy, strabismus, nystagmus and cataracts." (PMID 37239976, 2023).
limb-girdle muscular dystrophy (2 papers, 2015 to 2023). Limb-girdle muscular dystrophy (LGMD) is a heterogeneous group of muscular dystrophies characterized by proximal weakness affecting the pelvic and shoulder girdles. "At the mild end of the spectrum, mutations in GMPPB lead to the limb-girdle muscular dystrophy that is limited to a weakness in the proximal limb muscles." (PMID 26133662, 2015). "Interestingly, the only two patients in our cohort with an onset beyond childhood carried causative variants in GMPPB, a gene that has already been associated with late-onset CMS and limb-girdle muscular dystrophy." (PMID 36308527, 2023).
emphysema (1 paper, 2025). "Intersection analysis identified core COPD–lung cancer genes (UBA7, ZDHH5, GMPPB, IREB2, PYGB), with emphysema‐specific IREB2 (lung) and PSMA4 (blood)." (PMID 41377765, 2025).
endometrial cancer (1 paper, 2020). Primary or metastatic malignant neoplasm involving the endometrium (mucous membrane that lines the endometrial cavity). "Moreover, GMPPB overexpression is associated with a favorable prognostic value in endometrial cancer." (PMID 33425736, 2020).
fibromyalgia (1 paper, 2023). A chronic disorder of unknown etiology characterized by pain, stiffness, and tenderness in the muscles of neck, shoulders, back, hips, arms, and legs. "Several genes/loci have been reported more than once in CWP, fibromyalgia, and MCP, including EXD3, SLC39A8, AMIGO3/GMPPB/RNF123, C6orf106, FAF1, SLC24A3, and LINC01065/LINC00558." (PMID 37144689, 2023).
glioma (1 paper, 2023). A benign or malignant brain and spinal cord tumor that arises from glial cells (astrocytes, oligodendrocytes, ependymal cells). "Using the TCGA and GTEx databases to analyze GMPPB mRNA expression levels, we found that GMPPB was significantly upregulated in glioma tumors when compared to normal brain tissues." (PMID 37834154, 2023). "Here, we found that GMPPB is highly expressed in a panel of GBM cell lines and clinical samples and that expression of GMPPB is positively correlated with the WHO grade of gliomas." (PMID 37834154, 2023). "Analysis of mRNA expression in 698 cases in the TCGA database showed a reverse correlation between GMPPB expression and glioma." (PMID 37834154, 2023). "To support these results, we analyzed GMPPB expression in our 50 glioma clinical samples (collected from the Department of Neurosurgery at Sun Yat-sen University Cancer Center)." (PMID 37834154, 2023). "To evaluate if GMPPB expression was related to the malignant grades of gliomas, we analyzed data from TCGA and found that there is a positive correlation between GMPPB expression and the WHO grades of gliomas and that GBM tumors expressed the highest levels of GMPPB." (PMID 37834154, 2023).
muscular dystrophy-dystroglycanopathy (1 paper, 2015). "Mutations in GMPPB have recently been reported to lead to the onset of muscular dystrophy dystroglycanopathy." (PMID 26133662, 2015). "Mutations in GMPPB have been previously associated with the development of a muscular dystrophy dystroglycanopathy (MDDG), which is caused by the defective O-glycosylation of α-dystroglycan." (PMID 26133662, 2015). "Mutations in GMPPB can cause muscular dystrophy-dystroglycanopathy [MDDGA14 (MIM 615350), MDDGB14 (MIM 615351), MDDGC14 (MIM 615352)]." (PMID 26133662, 2015).
myasthenia (1 paper, 2015). "CMS due to GMPPB mutations may frequently remain undiagnosed due to lack of facial features usually associated with myasthenia, the presence of high creatine kinase levels and the restricted muscle groups that show decrement on repetitive nerve stimulation." (PMID 26133662, 2015).
tumor (3 papers, 2019 to 2023). "It is equally important to demonstrate that overexpression of GMPPB is strongly correlated with tumor cell proliferation, invasion, and metastasis in vivo." (PMID 37834154, 2023). "GMPPB is an important enzyme affecting the O-glycosylation of alpha-dystroglycan and N-glycosylation of beta-dystroglycan, and little is known about its role in tumor biology." (PMID 34496868, 2021). "The results showed that CLDN9, AK4, PC, GPC1, and SRD5A3 were upregulated in EC tissues compared to in normal endometrium tissues, whereas B4GALT1, GMPPB, B4GALT4, and CHST6 were downregulated in tumor tissues." (PMID 31807118, 2019).
muscular disorder (1 paper, 2023). "Given that the mutation is likely pathogenic and that disrupted GMPPB activity is pathogenic, we hypothesize that R357 methylation is required for complex formation and that the R357H mutation inhibits methylation and contributes to muscular disorder etiology." (PMID 36830724, 2023).
myopathies (1 paper, 2026). "Thanks to next‐generation sequencing analysis of large cohorts of patients with myopathies, GMPPB deficiency is emerging as a cause of muscle disease that is often overlooked and is probably more prevalent than expected." (PMID 41554119, 2026).
neurodevelopmental disorder (1 paper, 2023). A behavioral and cognitive disorder with onset during the developmental period that involves impaired or aberrant development of intellectual, motor, or social functions. "For example, all TRSs associated with ADHD include three genes, PNPLA2, PLK1S1 and GMPPB, previously associated with ADHD and/or other neurodevelopmental disorders." (PMID 37537283, 2023).
GMPPB also shares sentences with these, for which no sentence is quoted: Walker-Warburg syndrome (4 papers); Intellectual disability (2); cataract (1); Crohn disease (1); glioblastoma (1); lung carcinoma (1); metabolic myopathy (1); microcephaly (1); musculoskeletal system diseases (1); nicotine dependence (1); Nystagmus (1); ovarian carcinoma (1); Parkinson disease (1); Strabismus (1).